MGMT (O-6-methylguanine-DNA methyltransferase)
Diseases named in the same sentence as MGMT in open-access papers (continued):
Sharing a sentence is not in itself a finding about the gene and the disease.
tumor (continued). "The activity of MGMT consists in repairing DNA damage found during cell replication, including damage created by the action of chemotherapeutic drugs used as anticancer agents, which should block tumor growth." (PMID 38203299, 2023). "When adjusting for major clinical confounding factors (age, ECOG PS, tumor location, extent of surgical resection, second surgery, MGMT promoter methylation status), multivariable analysis confirmed the non-linear relationship between OS and baseline fT3/fT4 (p = 0.03)." (PMID 37264256, 2023). "Considering the high sensitivity of patients with MGMT promoter methylation to temozolomide, we speculate that in C2, the tumor growth could be control by temozolomide." (PMID 38161335, 2023). "Interestingly, IL-10 was over-expressed by all three monocyte subpopulations from patients with MGMT-unmethylated tumor compared to MGMT-methylated tumor." (PMID 36768201, 2023). "Nuclear immunostaining for MGMT was identified in 4 tumor samples." (PMID 37554223, 2023). "Despite the low VAF, the tumor tested positive for MGMT promoter methylation on the array." (PMID 37919784, 2023). "MGMT methylation status was related to the characteristics of the tumour at presentation." (PMID 37373988, 2023). "The expression of MGMT in tissues is variable, for example, there is a high protein expression in liver and lower expression in hematopoietic tissues; therefore, tumor MGMT expression is immensely variable, and consequently, its main role in treatment with alkylant agents." (PMID 37371106, 2023). "Indeed, stimulation with TMZ and AT101 resulted in higher cytotoxicity and better tumor growth control of MGMT promoter-methylated, patient-derived, primary GBM cells compared to a single TMZ treatment." (PMID 37240419, 2023). "A final strength of the current study is the level of annotative detail included in the co-variate modelling, spanning from steroid and antiepileptic medication usage to radiological tumour volume and molecular diagnostic sub-typing based on IDH and MGMT promoter status." (PMID 36836511, 2023). "MGMT-negative cases were associated significantly with larger tumor size (p < 0.01), higher Ki-67 index (p < 0.01), higher mitotic index (p < 0.05), and more frequent liver metastasis (p < 0.05)." (PMID 37161026, 2023). "Tumour cells containing methylated MGMT, as reported in the pathology notes." (PMID 37649945, 2023). "Similarly, ddPCR can detect MGMT promoter methylation in paucicellular tumor samples due to low background signals." (PMID 37919784, 2023). "Epigenetic MGMT promoter methylation has been shown to be associated with better clinical outcomes for patients treated with temozolomide (TMZ) and radiotherapy due to a decrease in tumor DNA repair." (PMID 37454191, 2023). "Also, the DNA repair enzyme O6-methylguanine-DNA methyltransferase (MGMT) is transported via TNTs from Temozolomide (TMZ)/irradiation (IR)-resistant cells to tumor-sensitive cells, likely to prevent cell death." (PMID 37476291, 2023). "However, despite this, favourable MGMT promoter methylation status is unfortunately not sufficient to confer acceptable long-term survival, with 5-year survival rates even for patients with tumours with methylated MGMT promotor regions is only around 14%." (PMID 37777579, 2023). "Also, this therapy encounters tumor cell resistance to TMZ conferred by unmethylated MGMT, thereby decreasing the responsiveness of the therapy." (PMID 37371047, 2023). "Therefore, those patients with MGMT promoter methylation in GBM tumor cells respond better to temozolomide treatment and live longer." (PMID 37928546, 2023). "Therefore, coadministration of PARP inhibitors (olaparib, niraparib, rucaparib, and talazoparib) with TMZ or procarbazine is anticipated to ameliorate tumor cytotoxicity in the presence of MGMT." (PMID 38068493, 2023).
tumor (continued). "SUVmax on TSPO PET, TSPO binding affinity status, tumor volumes on MRI, and further clinical data, such as O6-alkylguanine DNA methyltransferase (MGMT) and telomerase reverse transcriptase (TERT) gene promoter mutation status, were correlated with patient survival." (PMID 37536737, 2023). "Application of the assays to primary human tumor cell lines derived from GBM patients revealed that the DNA methylation status of MGMT enhancers 2, 3, and 4 is associated with MGMT promoter methylation and/or MGMT protein expression." (PMID 38136323, 2023). "However, novel treatment options for recurrent GBM, especially addressing tumours with unmethylated MGMT and resistance to temozolomide, are urgently needed." (PMID 36730349, 2023). "Inhibition of MGMT effectively enhances the sensitivity of tumor cells to antitumor drugs." (PMID 38202657, 2023). "Although it has little correlation with stromal, immune scores and tumor purity, the MGMT promoter mutation did not exhibit this trend." (PMID 37091145, 2023). "Thus, a higher degree of MGMT promoter methylation was related to better performance status at presentation, lower initial tumour volume and a higher extent of resection." (PMID 37373988, 2023). "Additionally, high rates of local tumor control were reported with concomitant chemoradiotherapy as salvage treatment for patients with aggressive PA or PC, especially in patients with MGMT promotor methylation." (PMID 36157469, 2022). "However, a hypoxic tumor microenvironment appears to establish the therapeutically inferior MGMT status." (PMID 34687436, 2022). "Tumor cells that overexpress the MGMT repair protein could be capable of blocking the therapeutic effects of alkylating drugs." (PMID 35806212, 2022). "Recent research has proven that MGMT is a key component in tumour prognosis." (PMID 35565282, 2022). "Existing research indicates that MGMT acts as a tumor suppressor in HCC." (PMID 35723009, 2022). "While the mean age, gender distribution, preoperative KPS score, mean tumor volume, the incidence of ventricle infringement, MGMT promoter status, EFGR amplification, tumor location, and TERT promoter status was not different between discordant and accordant patients." (PMID 35185770, 2022). "Tumor CcO activity and MGMT promoter methylation status were assayed in a centralized laboratory." (PMID 35088051, 2022). "The very limited effect in pediatric patients might be due to the fact that pediatric GBM tumor cells display MGMT promotor methylation significantly less often." (PMID 35681794, 2022). "Therefore, MGMT expressed in tumor cells removes the guanine alkyl group and attenuates its antitumor effects." (PMID 36291588, 2022). "Two intron variant SNPs of MGMT and STARD3 were identified that were significant survival predictors and may influence tumor biology." (PMID 34529172, 2022). "However, this leaves the difficulty to decide on a cutoff value, i.e., for the average methylation of a limited number of CpGs in the MGMT promoter that should ideally reflect on the MGMT activity in the tumor, which is until now rather difficult to obtain." (PMID 35180887, 2022). "However, future studies in larger cohort should additionally take into consideration different parameters, such as MGMT promoter methylation, extent of tumor resection, tumor enhancement, and treatment." (PMID 36400876, 2022). "Indeed, pathological diagnostic results indicated a high level of MGMT expression and high percentage of KI67+ (also known as MKI67+) tumor cells (#p3 60%, #p4 50%) in the two patients with relapse." (PMID 35199829, 2022).
tumor (continued). "The higher rate of radionecrosis in the HF-RT group may be related to the higher proportion of tumour MGMT methylation in the group." (PMID 36355260, 2022). "Among patients in this study with known tumor MGMT status, 51% had mMGMT." (PMID 34510238, 2022). "However, it was shown that pediatric GBM tumor cells display MGMT promoter methylation significantly less often and, therefore, showed a less effective response to TMZ as expected." (PMID 35681794, 2022). "The benefit from combined radio-chemotherapy was particularly significant among patients with MGMT promoter-methylated tumours, who displayed a median overall survival of 13.5 months compared to only 7.7 months in the radiotherapy group (HR = 0.53; p < 0.0001)." (PMID 35327445, 2022). "Indeed, IDH1/2 mutations have been established as the most powerful positive prognostic factor for glioma patient survival, followed by age, tumor grade and MGMT gene methylation status." (PMID 35806153, 2022). "The MGMT gene is a classic tumor suppressor gene, and the MGMT protein is a DNA repair enzyme." (PMID 35855654, 2022). "MGMT silencing only occurred in radiation-primed tumor sites in the subcutaneous tumor model." (PMID 33850305, 2022). "This was likely due to 10 of the 48 patients (20.8%) exhibiting tumor shrinkage before the time of radiographic recurrence (1 of these 10 were MGMT promoter methylated) and another 15 of the 48 patients (31.3%) exhibiting tumor recurrence due to an unmeasurable new lesion." (PMID 36053452, 2022). "The habitat profile of a tumour may correlate with key molecular changes such as O6-methylguanine-DNA methyltransferase (MGMT) promotor methylation, which could non-invasively aid the selection of patients for future neoadjuvant trials." (PMID 36505856, 2022). "However, TMZ resistance is seen in tumor cells expressing the direct repair protein O6-methylguanine-DNA methyltransferase (MGMT)." (PMID 35892832, 2022). "Our group reported that loss of MGMT expression via MGMT promoter silencing modulates activation of ataxia telangiectasia and RAD3 related protein (ATR) in response to TMZ treatment, which is associated with synergistic tumor-cell killing." (PMID 35388070, 2022). "Understanding the relationship between MGMT protein expression, MGMT methylation and acquisition of MMRd, and the rate of increased acquisition of tumour mutation burden after TMZ and the relationship between Tumour Mutational Burden (TMB) acquisition and response to nivolumab will be explored." (PMID 36050653, 2022). "However, tumor tissue and sequencing patterns would be necessary to properly investigate the effect of MGMT expression (and PGAP3, respectively) on actual prognosis for the separate TCGA subtypes." (PMID 34529172, 2022). "In the past, the alkylating agent temozolomide (TMZ) has been investigated for AML and found to be partially effective; however, the presence of O6-methylguanine DNA methyltransferase (MGMT; a DNA repair enzyme) in tumor cells confers profound treatment resistance against TMZ." (PMID 36551551, 2022). "Encapsulation of an antitumor drug with subsequent controlled release and an extended half-life helps to reduce the toxic effect of TMZ on healthy tissues, protects temozolomide from premature physiological degradation due to MGMT, and delivers it directly to tumor cells." (PMID 35684445, 2022). "In addition, MGMT promoter methylation status, IDH mutation status, expression level of Ki67, tumor location, MRI somatotype, postoperative KPS and TMZ cycles were favorable factors for progression-free survival." (PMID 36483042, 2022). "It has been observed that the patients with tumor with methylated MGMT promoter have better survival rate when treated with combination therapy (radiation therapy along with chemotherapy with TMZ) as compared to those having unmethylated MGMT promoter tumor." (PMID 36185622, 2022).
tumor (continued). "However, for tumor cells, abnormally expressed MGMT specifically removes the lesions at the guanine O6 position, resulting in resistance of tumor cells to guanine O6-alkylating agents like TMZ." (PMID 37077808, 2022). "The nomograms were constructed by combining all the independent prognostic markers, namely, tumor grades, ALKBH5 mRNA expression levels, IDH mutation status, 1p/19q codeletion status and MGMT promoter status, based on the results of the Cox regression analysis." (PMID 35444654, 2022). "Furthermore, WB analysis confirmed that MGMT protein expression was downregulated in tumour tissue in the shRNA-circWDR62 group compared to the shRNA-NC group." (PMID 35817771, 2022). "Within the study cohort, 100 (61%) patients had evaluable tumor tissue for MGMT expression by IHC." (PMID 35621918, 2022). "Furthermore, the effectiveness of this therapy is highly dependent on the genetic properties of the tumor, namely, the methylation status of the O-6-methylguanine-DNA methyltransferase (MGMT) promotor." (PMID 35628643, 2022). "Higher ADC values may predict MGMT promoter methylation status and a longer overall survival rate, thereby reflecting lower tumor cellularity in the methylated group." (PMID 36289752, 2022). "Besides, tumor cells expressing 6- methylguanine-DNA methyltransferase (MGMT) can counteract the methylation of guanine induced by TMZ, exhibiting resistance to the drug." (PMID 36613792, 2022). "Group TT of rs12268840 showed the highest rate of second primary carcinomas, lowest mRNA expression of MGMT in normal tissue, and worst oncologic outcome, implicating that rs12268840 could be involved in tumor progression." (PMID 34529172, 2022). "Proteins DAPK1 (Death-associated proteinkinase 1), MGMT (Methylated-DNA-protein-cysteine methyltransferase),and SOCS1 (Suppressor of cytokine signaling 1)are considered tumor suppressors, and their low expressionin carcinomas correlates with disease progression." (PMID 36714033, 2022). "Silencing MGMT or ALKBH5 of GBM tumor cells could inhibit GAM infiltration and repress NEAT1 and CXCL8 expression, eventually suppressing GBM tumor cell growth and lengthening the survival of GBM patients." (PMID 35572545, 2022). "Tumours which are MGMT methylated are sensitive to temozolomide." (PMID 36050653, 2022). "However, identifying the MGMT methylation status using molecular techniques remains challenging due to technical limitations, such as the inability to obtain tumor specimens, high prices for detection, and the high complexity of intralesional heterogeneity." (PMID 35927323, 2022). "In addition, previous studies showed that levetiracetam inhibited tumor cell growth by decreasing the expression of O6-methylguanine-DNA methyltransferase (MGMT)." (PMID 36447028, 2022). "The lower the degree of MGMT expression, the better the tumour’s response to TMZ treatment." (PMID 35683457, 2022). "The edema region resulted as the top-performing region in the prediction of MGMT status using multivariate analysis (AUC 0.78); the inverse variance feature from gray level co-occurrence matrix in whole tumor, instead, had the best performance using univariate analysis (p-value = 0.002)." (PMID 36551961, 2022). "Therefore, it would be highly desirable to develop methods to selectively target the MGMT-inactivating medication to the tumor." (PMID 36009577, 2022). "Nevertheless, these anti-tumor effects induced by MGMT overexpression could be abolished by miR-221-3p upregulation." (PMID 35723009, 2022). "Thus, a tumor sample was evaluated positively for the methylation of the MGMT promoter in the case of either a hypermethylated MSP evaluation (M/U > 1) or a positive qMSP evaluation based on the PMR > 100% cut-off values." (PMID 36361838, 2022).
tumor (continued). "Tumor DNA was extracted from these samples, and pyrosequencing analysis revealed that 5 CpG regions of the MGMT promoter were intermediate methylated, which could be indicated by the average percentage of methylated CpG site in the mean range of 10–26%." (PMID 35646111, 2022). "Indeed, in an initially TMZ-responsive tumor cell population, resistance can easily be acquired by upregulating DNA-repairing enzymes such as MGMT or by inactivating the DNA mismatch repair (MMR) system, eventually leading to tumor recurrence." (PMID 35955765, 2022). "DNA Methylation profiling showed unmethylated MGMT promoter; there was no 1p and 19q loss in copy number profiling and allocated the tumor to the methylation class of glioblastoma IDH wildtype, subclass RTK I." (PMID 35018523, 2022). "Tumor cells were positive for MGMT, IDH1, and H3K27M, with Ki-67 of 7%." (PMID 35991838, 2022). "Tumor MGMT promoter methylation status was undetermined for 26 participants." (PMID 35088051, 2022). "Patients with an O6-methylguanine DNA methyltransferase (MGMT) promoter-methylated recurrent tumour may benefit from a temozolomide rechallenge, from lomustine or even the combination of both." (PMID 36333718, 2022). "Tumor cells were positive for MGMT and IDH1, with a proliferation activity of 4% for Ki-67." (PMID 35991838, 2022). "Interestingly, the combination was previously found to be ineffective in MGMT‐unmethylated cell lines, suggesting the predicting value of MGMT promoter methylation status in tumor response to TMZ/veliparib combination therapy." (PMID 34977872, 2021). "We have therefore devised a new treatment strategy involving the use of a multidrug combination, including IFN-β in the initial induction therapy administered with RT, followed by maintenance therapy with TMZ and IFN-β administered for as long as possible, aimed at depleting tumor MGMT." (PMID 34320929, 2021). "This was the case for MGMT in the necrotic area or PTEN in the tumor area, for instance." (PMID 35047379, 2021). "GL26 cells had no MGMT expression 48, and MGMT expression of SB28 is unknown 49, therefore, whether the anti-tumor effect of TMZ in Nhe1 KO mice is dependent on MGMT methylation status or TMZ-induced ER stress remains to be investigated." (PMID 33391535, 2021). "Several factors are attributed to GBM prognosis, depending on clinical and biological patient parameters, such as age and extent of resection, or based on the characteristics of the tumor at the molecular level, such as IDH mutation or MGMT promoter methylation." (PMID 34577582, 2021). "MGMT removes alkyl groups from guanine in the DNA, potentially counteracting the therapeutic efficacy of alkylating chemotherapeutics, such as temozolomide, in tumor cells." (PMID 34771583, 2021). "Blocking TNT prevented MGMT diffusion and the survival of tumor cells with minimal MGMT expression." (PMID 34267246, 2021). "Our study shows us that changes in the expression levels of MMR and MGMT proteins may result in tumor growth and/or progression of thyroid neoplasia." (PMID 33976347, 2021). "However, in comparison to patients after CR, a methylated MGMT promoter cannot compensate the disadvantage due to residual tumor volume." (PMID 34185258, 2021). "The pooled ORs showed a significant association between specific tumor-related genes and HNC risk: p16 (3.75; 95% CI = 2.51–5.60), MGMT (5.72; 95% CI = 3.00–10.91), DAPK (5.34; 95% CI = 2.18–13.10), TIMP3 (3.42; 95% CI = 1.99–5.88), and RASSF1A (7.69; 95% CI = 3.88–15.23)." (PMID 34206840, 2021). "Tumour tissue from forty-five patients were comprehensively analysed for IDH1 or IDH2 mutations and methylation of sixteen sites (CpG’s 74–89) in the CpG island of the MGMT gene." (PMID 34209555, 2021).